SNORA14B (small nucleolar RNA, H/ACA box 14B)
Synonyms: ACA14b
Gene: Small nucleolar RNA gene on chromosome 1 (235,127,803 to 235,127,937, reverse strand). Ensembl gene ENSG00000207181.
Gene Ontology:
Biological process: RNA processing
Cellular component: nucleolus
Homologues: Orthologues: macaque SNORA14B (99% identical), mouse Gm26397 (91% identical), rat LOC120098679 (90% identical). Paralogues in human: SNORA14A (91% identical).